LMO4 (LIM domain only 4)
Description:
Transcription cofactor. Plays a role in establishing motor neuron identity, in concert with MNX1, acting, at least in part, to disrupt LDB1-LHX3 complexes thereby negatively modulating interneuron genes in motor neurons.
Tractability: No criterion of Open Targets' tractability assessment is met for any kind of drug.
Gene: Protein-coding gene on chromosome 1 (87,328,428 to 87,348,923, forward strand). Ensembl gene ENSG00000143013.
Subcellular location (Human Protein Atlas): Nucleoplasm; Cytosol; Midbody ring
Gene Ontology:
Molecular function: protein binding; DNA-binding transcription factor binding; transcription coregulator activity; transcription corepressor activity
Biological process: neural tube closure; positive regulation of kinase activity; positive regulation of transcription by RNA polymerase II; regulation of cell migration; spinal cord motor neuron cell fate specification; motor neuron axon guidance; negative regulation of transcription by RNA polymerase II; regulation of developmental process; tissue development
Cellular component: cell leading edge; nucleus; transcription regulator complex; RNA polymerase II transcription regulator complex
Genetic constraint (gnomAD): Loss-of-function variants: 1 observed, 14.4 expected, observed/expected ratio (o/e) 0.0695, 90% interval 0.024 to 0.33. The upper end of that interval is the gene's LOEUF score, 0.33, which puts it in group 1 of 6, group 1 being the genes least tolerant of losing a copy. Missense variants: 113 observed, 218.8 expected, observed/expected ratio (o/e) 0.52, 90% interval 0.44 to 0.6. Synonymous variants: 95 observed, 90.41 expected, observed/expected ratio (o/e) 1.05, 90% interval 0.89 to 1.25.
Homologues: Orthologues: chimpanzee LMO4 (100% identical), guinea pig LMO4 (100% identical), mouse Lmo4 (100% identical), rabbit LMO4 (100% identical), macaque LMO4 (99% identical), rat Lmo4 (99% identical), zebrafish lmo4b (96% identical), tropical clawed frog lmo4 (90% identical). Paralogues in human: LHX9 (41% identical), LMX1B (41% identical), LHX2 (39% identical), LMO1 (39% identical), LMO3 (38% identical), LHX8 (37% identical), LMO2 (37% identical), LMX1A (37% identical), LHX6 (36% identical), ZFHX3 (35% identical), LHX3 (34% identical), ZFHX4 (34% identical), and 8 more.
Diseases named in the same sentence as LMO4 in open-access papers:
LMO4 is named in the same sentence as 45 diseases in open-access papers, as found by Europe PMC text mining. Sharing a sentence is not in itself a finding about the gene and the disease. The quoted sentences say what the papers report.
breast carcinoma (18 papers, 2002 to 2025). "Overexpression of LMO4 appears to be associated with more aggressive behavior and poorer survival in many cancers, like gastric cancer cells, breast cancer and NSCLC." (PMID 39408743, 2024). "Accumulating evidence suggests that LMO1 and LMO2 act as oncogenic proteins in T-cell acute lymphoblastic leukemia, whereas LMO4 has recently been implicated in the genesis of breast cancer." (PMID 16420690, 2006). "LMO1 and LMO2 overexpression is linked to T-cell tumourigenesis and LMO4 has been associated with breast oncogenesis, where overexpression is observed in approximately 50% of breast cancer cell lines and primary breast cancers." (PMID 16280053, 2005). "LMO4 demonstrates variable expression in different cancers but its role remains unclear since in breast cancer, high LMO4 expression is associated with a poor prognosis, while in pancreatic cancer it is associated with a better survival." (PMID 22355404, 2012). "One example is 1p22.3, where CHiCAGO-detected interactions in the VCHi-C data between two independent signals and the LIM-only protein 4 (LMO4) promoter in Hs578T breast cancer cells." (PMID 31910858, 2020). "LMO4 is overexpressed in more than 50 % of breast cancers and high nuclear expression of LMO4 has been found to be a predictor of worse outcome in breast cancer patients." (PMID 26048572, 2015). "LIM-domain only protein 4 (LMO4) is a widely expressed protein with important roles in embryonic development and breast cancer." (PMID 25310299, 2014). "In 2005, Sum and colleagues reported that LMO4 mRNA was overexpressed in 5 of 10 human breast cancer cell lines; in situ hybridization analysis of 177 primary invasive breast carcinomas revealed overexpression of LMO4 in 56% of the specimens." (PMID 19099607, 2008). "Conversely, overexpression of LMO4 has been observed in greater than 50% of human breast cancers and Lmo4 is oncogenic when overexpressed in the mammary glands of transgenic mice." (PMID 18826651, 2008). "The transcription factor DEAF-1 has been identified as a high affinity binding partner of the LIM-only protein LMO4 that plays important roles in mammary gland development and breast cancer." (PMID 18826651, 2008). "We sought to carry out mutation analysis of FANCD2, BRIP1/BACH1, LMO4 and SFN in a large number of non-BRCA1/2 breast cancer families." (PMID 16280053, 2005). "Moreover, regulators such as TFAP2C, GTF2I and LMO4 were found to have potential prognostic value for lung metastasis free (LMF) survival of breast cancer." (PMID 31215771, 2019). "In addition, the LIM (Lin11, Isl-1, and Mec-3) domain-containing protein LMO4 (LIM-only protein 4) is highly expressed in breast cancer, and its aberrant expression leads to centrosome amplification and defects in spindle formation." (PMID 26893288, 2016). "LMO4 is overexpressed in 50 % of breast cancer and 83 % of pancreatic adenocarcinoma." (PMID 26048572, 2015). "Aside from breast cancer, LMO4 is overexpressed in non-small-cell lung cancer." (PMID 25310299, 2014). "Subsequent disruptions to the normal expression patterns and subcellular localisation of LMO4 could therefore contribute to severe developmental abnormalities and breast cancer." (PMID 25310299, 2014). "Furthermore, its interacting partner LMO4 is upregulated in breast cancer and promotes breast tumorigenesis." (PMID 25079073, 2014). "Of these, the transcriptional regulator LMO4, may be of particular interest, as it is well studied as an oncogene in breast cancer and regulated through the phosphoinositide 3-kinase pathway, which is commonly affected in glioblastoma." (PMID 23046790, 2012). "We hypothesized that germline mutations in FANCD2, BRIP1/BACH1, LMO4 and SFN may account for some of the unexplained multiple-case breast cancer families." (PMID 16280053, 2005).
breast carcinoma (continued). "Importantly, genes involved in EMT were also found to be down‐regulated in LMO4 decreased LM2‐4175 cells, suggesting that LMO4 may regulate the EMT process in breast cancer lung metastasis." (PMID 31215771, 2019). "Conversely, LMO4, another LIM domain protein, is broadly expressed in human tissues, including over 50% of breast tumors, where it reduces the differentiation of breast cancer epithelial cells and functions as an oncogene." (PMID 40076569, 2025). "LMO4, a LIM-only transcriptional regulator, was reported to induce breast cancer invasion and predict poor outcomes." (PMID 36347834, 2022). "Our CHIP-seq and CHIP-qPCR data showed a similar pattern in breast cancer cells.: HNRNPU and DDX5 are enriched in the TSS of LMO4 and then activate LMO4 transcription." (PMID 36347834, 2022). "LIM-only 4 (LMO4), a member of the LIM-only (LMO) subfamily of LIM domain-containing transcription factors, was initially reported to have an oncogenic role in breast cancer." (PMID 19099607, 2008). "It appears unlikely, therefore, that FANCD2, BRIP1/BACH, LMO4 and SFN account for more than a small proportion of inherited forms of breast cancer." (PMID 16280053, 2005). "Intriguingly, these functions may parallel the proliferative, migratory and invasive functions ascribed to LMO4, a partner of DEAF-1, in human breast cancer cell lines." (PMID 18826651, 2008). "Although Lmo4 transgenic mice develop hyperplasia and mammary intraepithelial neoplasia or adenosquamous carcinoma, overexpression of Deaf-1 did not lead to mammary tumors." (PMID 18826651, 2008). "We therefore hypothesized that germline mutations in the BRCA1-interacting genes, FANCD2, BRIP1/BACH1, LMO4 and SFN, may account for some non-BRCA1/2 multiple-case breast cancer families." (PMID 16280053, 2005). "Mutation analysis of the BRCA1-interacting genes FANCD2, BRIP1/BACH, LMO4 and SFN in a large number of non-BRCA1/2 breast cancer families did not identify any highly penetrant, pathogenic mutations." (PMID 16280053, 2005). "LMO7 in gastric cancer has not been dealt with in any reports, but another isoform, LMO4 (a transcriptional regulator) inhibits differentiation of mammary epithelial cells in vitro and is overexpressed in breast cancers." (PMID 12402156, 2002).
breast tumors (3 papers, 2014 to 2025). "LMO4 is a transcriptional modulator that is overexpressed in > 50% of breast tumors." (PMID 31910858, 2020).
gastric cancer (3 papers, 2002 to 2024). A primary or metastatic malignant neoplasm involving the stomach. "LMO4 is an oncogene and was reported to promote the invasion and proliferation of gastric cancer by activating PI3K/Akt/mTOR signalling." (PMID 36347834, 2022).
head and neck squamous cell carcinoma (3 papers, 2015 to 2025). A squamous cell carcinoma that arises from any of the following anatomic sites: lip and oral cavity, nasal cavity, paranasal sinuses, pharynx, larynx, and salivary glands. "In head and neck squamous cell carcinomas, LMO4 has been reported to be overexpressed at the invasive front of the tumor but its expression did not correlate with patient outcome." (PMID 26048572, 2015). "In head and neck squamous cell carcinoma (HNSCC), LMO4 is overexpressed at tumor invasion fronts and in lymph node metastases, where it interacts with LIM domain-binding protein 1 (LDB1) and shows enhanced nuclear localization." (PMID 41213908, 2025).
neuroblastoma (3 papers, 2014 to 2020). Neuroblastoma (NB) is the most common solid, extracranial childhood tumor. "LMO4 (LIM domain only 4) has been shown to be an essential cofactor in EMT at least in neuroblastoma and neural crest cells." (PMID 32252623, 2020). "LMO4 is a transcriptional regulator involved in the epithelial-to-mesenchymal transition of neuroblastoma and neural crest cells." (PMID 28187790, 2017). "Lmo4, a vertebrate homolog of Bx is known to affect the number of neurite outgrowths and their length in human SH-SY5Y neuroblastoma cells." (PMID 25396431, 2014).
pancreatic cancer (3 papers, 2008 to 2019). "In conclusion, the present results showed that LMO4 is overexpressed in pancreatic cancer related to both the PanIN-conventional IDC pathway and the IPMA-IPMC pathway, but not at the early stages of pancreatic carcinogenesis." (PMID 19099607, 2008). "In the present study, LMO4 mRNA was not overexpressed in any of the 14 pancreatic cancer cell lines." (PMID 19099607, 2008).
Anxiety (2 papers, 2012 to 2023). Intense feelings of nervousness, tension, or panic often arise in response to interpersonal stresses. "Previous studies have shown that Lmo4 regulates synaptic plasticity in the adult hippocampus and that Zfp462 is related to anxiety-like behaviors, suggesting its possible roles in subtype specification and functional maintenance in the MP." (PMID 36791184, 2023). "To determine whether Lmo4 has a role in learned as well as unlearned (innate) fear, we compared anxiety-like behavior in WT and Lmo4gt/+ mice as well as mice in which Lmo4 levels were down-regulated in the BLC using shRNA." (PMID 22509321, 2012). "It is however possible that knockdown of Lmo4 globally or in the BLC may lead to very subtle effects on anxiety-like behavior which we were unable to detect due to repeated testing." (PMID 22509321, 2012). "Since LMO4 is predominantly expressed in glutamatergic projection neurons of the BLC, we sought to determine whether reduction in Lmo4 levels had an impact on anxiety-like behavior." (PMID 22509321, 2012). "Taken together, these results argue against a role for Lmo4 in anxiety like-behavior." (PMID 22509321, 2012). "Lastly, we measured anxiety-like behavior in Lmo4gt/+ mice and in mice with BLC-specific downregulation of Lmo4 using the elevated plus maze, open field, and light/dark box tests." (PMID 22509321, 2012). "Taken together, these results suggest that Lmo4 functions in the BLC to specifically affect learned but not innate fear or anxiety." (PMID 22509321, 2012). "Our results with Lmo4gt/+ mice suggest that reductions in Lmo4 levels in several brain regions implicated in unlearned fear such as the hippocampus, PFC, and amygdala do not affect anxiety-like behavior." (PMID 22509321, 2012). "Reduction in Lmo4 levels does not affect anxiety-like behavior." (PMID 22509321, 2012). "Global or BLC-specific knockdown of Lmo4 did not significantly affect anxiety-like behavior." (PMID 22509321, 2012). "ShRNA-mediated knockdown of Lmo4 in the BLC in adults also did not alter anxiety-like behavior." (PMID 22509321, 2012).
Obesity (2 papers, 2023 to 2024). Accumulation of substantial excess body fat. "Intriguingly, we observed a significantly lower expression of hepatic Lmo4 after blocking M3R by Olanzapine in female rats, which resulted in weight gain, obesity, and lipid metabolic dysfunction." (PMID 39061977, 2024). "The essential role played by PTP1B inhibition in the anti-obesity and antidiabetic activities of trodusquemine was confirmed by studies on the LIM domain only 4 (LMO4) protein, an endogenous negative regulator of PTP1B." (PMID 37298571, 2023).
pancreatic ductal adenocarcinoma (2 papers, 2009 to 2019). An infiltrating adenocarcinoma that arises from the epithelial cells of the pancreas. "LMO4 is a transcription regulator and increased expression of LMO4 in pancreatic ductal adenocarcinoma is associated with a survival advantage." (PMID 19497108, 2009).
squamous cell carcinoma (2 papers, 2003 to 2015). A carcinoma arising from squamous epithelial cells. "In a cohort of 84 NSCLC resected specimen from patients with stage I and II disease, we found that LMO4 expression was significantly higher in squamous cell carcinoma compared to adenocarcinoma." (PMID 26048572, 2015). "Expression of LMO4, LDB1, and LDB2 in squamous cell carcinomas has not been investigated." (PMID 12771919, 2003).
apraxia (1 paper, 2024). Apraxia is a neurological disorder characterized by the inability to perform tasks or movements, despite having the desire and physical ability to perform them. "In addition, Lmo4 and Sox5, which have been shown to participate in neuron differentiation with SOX5 being clinically associated with an NDD with apraxia of speech." (PMID 38238293, 2024).
attention deficit-hyperactivity disorder (1 paper, 2018). A disorder characterized by a marked pattern of inattention and/or hyperactivity-impulsivity that is inconsistent with developmental level and clearly interferes with functioning in at least two settings (e.g. at home and at school). "Additionally, six genes displaying at least differential expression among hemispheres (BAIAP2, DAPPER1, LMO4, NEUROD6, ATP2B3, and ID2) in a case-control association study in an initial Spanish sample of ADHD (Attention Deficit Hyperactivity Disorder) patients and control subjects." (PMID 30081481, 2018).
coloboma (1 paper, 2010). An abnormality in which a part of a structure in one or both eyes is missing. "Our observation of coloboma in LMO4 germline deleted mice, reported here for the first time, lead us to explore the function of LMO4 in retinal development." (PMID 20949055, 2010). "In phenotyping LMO4 null mice, we identified several features of altered eye development including smaller eyes and the presence of a coloboma phenotype in ∼40% of embryos." (PMID 20949055, 2010).
head and neck cancer (1 paper, 2022). A primary or metastatic malignant neoplasm affecting the head and neck. "LMO4 also belongs to a family of proteins that regulate transcription and they have been found to be related to several cancers such as leukemia, breast, and head and neck cancer." (PMID 35629174, 2022).
lung adenocarcinoma (1 paper, 2015). A carcinoma that arises from the lung and is characterized by the presence of malignant glandular epithelial cells. "The role of Lmo4 in lung tumorigenesis was measured using a mouse model of lung adenocarcinoma in which the oncogenic K-Ras protein has been knocked into the K-Ras locus." (PMID 26048572, 2015).
lung carcinoma (1 paper, 2015). "The observation that Lmo4 knockout mice display breathing difficulty at birth and that LMO4 is overexpressed in advanced lung cancer prompted us to explore its role in lung morphogenesis, adult lung repair and cancer." (PMID 26048572, 2015). "In lung cancer, gene expression analysis showed that LMO4 is overexpressed in SCLC and advanced adenocarcinoma but its expression has not been investigated in early stage disease in NSCLC." (PMID 26048572, 2015).
lung squamous cell carcinoma (1 paper, 2015). "Depletion of Lmo4 in a mouse model of lung squamous cell carcinoma would enable to further explore this hypothesis." (PMID 26048572, 2015). "A role for Lmo4 in the regulation of cells proliferation in long-term injury may provide information regarding its role in the pathology of lung squamous cell carcinoma." (PMID 26048572, 2015).
melanoma (1 paper, 2024). A malignant, usually aggressive tumor composed of atypical, neoplastic melanocytes. "We transduced pmel-1 Ly5.1+ T cells (which recognize the shared melanoma–melanocyte differentiation antigen gp100) with Lmo4-Thy1.1 or Thy1.1 and transferred them into wild-type mice infected with gp100-vv." (PMID 39117617, 2024).
oral carcinomas (1 paper, 2003). "Although GATA expression in oral carcinomas is not yet known, it could be intriguing if misexpression of LMO4 results in substitution of GATA to SNAIL/SIP1 and inhibits carcinoma cell differentiation." (PMID 12771919, 2003).
oral cavity carcinoma (1 paper, 2016). A carcinoma arising in the oral cavity. "A role for LDB1 and its LIM domain partner protein LMO4 in metastasis was suggested from the location of these proteins in oral cavity carcinoma, a finding which we extended to also include oropharyngeal carcinoma." (PMID 27780223, 2016).
oropharyngeal carcinoma (1 paper, 2016). Carcinoma, predominantly squamous cell, arising from the epithelial cells of the oropharynx. "The similarity in the frequency and localization of LMO4, LDB1, and SSBP2/3 expression in oral cavity and oropharyngeal carcinomas, by contrast, suggest these proteins subserve common functions in HNSCC regardless of etiology." (PMID 27780223, 2016).
tongue squamous cell carcinoma (1 paper, 2023). A squamous cell carcinoma that arises from the tongue. "In tongue squamous cell carcinoma (TSCC), linc-ROR was highly expressed, upregulating the expression of the LIM domain only 4 (LMO4) gene to promote the activation of the AKT/PI2K signaling pathway, stimulating cell proliferation and invasion." (PMID 36827545, 2023).
type 2 diabetes (1 paper, 2015). "We selected 14 disallowed genes for analysis based on their identification in 2 independent studies (C1qbp, Cd302, Cxcl12, Igfbp4, Ldha, Lmo4, Maf, Oat, Pdgfra, Slc16a1, and Smad3) and/or other criteria including up-regulation in type 2 diabetes (Acot7, Ldha, and Pdgfra)." (PMID 26038943, 2015).
Wilms tumor (1 paper, 2024). An embryonal neoplasm characterized by the presence of epithelial, mesenchymal, and blastema components. "Additionally, given the structural similarity of the LMO gene family, we reasonably speculated that LMO2 and LMO4 gene polymorphisms might be correlated to Wilms tumor susceptibility as LMO1 gene did." (PMID 38937681, 2024). "For the LMO4 gene, there were no obviously significant correlations between the rs3766019 G > A polymorphism and Wilms tumor susceptibility." (PMID 38937681, 2024).